ALDH2 (aldehyde dehydrogenase 2 family member)
Diseases named in the same sentence as ALDH2 in open-access papers (continued):
Sharing a sentence is not in itself a finding about the gene and the disease.
liver disease (14 papers, 2018 to 2026). "Mutations in the ALDH2 gene lead to impaired ALDH2 enzymatic activity, exacerbating the progression of liver diseases." (PMID 39669199, 2024). "Recently, cumulative evidence has revealed that ALDH2 plays an important role in liver diseases associated with the autophagy signal pathway." (PMID 35237626, 2022). "ALDH2 is the most studied aldehyde dehydrogenase, which are associated with decreased enzymatic activity, liver disease, cirrhosis, or pancreatitis in alcoholics." (PMID 36258220, 2022). "This review summarizes new progress in understanding tissue-specific acetaldehyde metabolism by ALDH2 as well as the association of ALDH2 gene polymorphisms with liver disease and cancer." (PMID 32140062, 2020). "In this review, we mainly summarized recent progress in understanding tissue-specific acetaldehyde metabolism by ALDH2 as well as the ALDH2 gene polymorphisms associated with the pathogenesis of liver disease and cancer." (PMID 32140062, 2020). "Our results suggest that potential changes in gut microbiota may be associated with the defective ALDH2 exacerbation of high-fat-diet-induced liver diseases in male mice." (PMID 34439969, 2021). "Sixth, it is possible that flushing response may diminish in intensity after a long or heavy drinking history, potentially leading to some misclassifications which might underestimate any heterogeneity in alcohol-liver disease risk relations by ALDH2 deficiency." (PMID 34530818, 2021). "Genetic polymorphisms in ALDH2 and ADH1B are key determinants of individual alcohol sensitivity and are significant in the progression and natural history of liver disease." (PMID 40943250, 2025). "Accumulated toxic aldehydes in the liver can be effectively metabolized by mitochondrial aldehyde dehydrogenase 2 (ALDH2), thereby alleviating various liver diseases." (PMID 39669199, 2024). "As discussed in the previous section, inhibition of ALDH2 activity can lead to the suppression of alcohol-induced liver diseases, and isoflavone analogues have gained attention as promising drug candidates to inhibit ALDH2 activity." (PMID 36923641, 2023). "Alcohol dehydrogenase 1B (ADH1B) and aldehyde dehydrogenase 2 (ALDH2), members of the alcohol dehydrogenase family, have important roles in liver diseases." (PMID 35237626, 2022). "Recently, multiple studies have suggested that ALDH2 is involved in the course of autophagy in a variety of liver diseases." (PMID 35237626, 2022). "As is known to all, the abnormal expression of ADH2 and ALDH2 genes in the liver is extremely related to the occurrence of various liver diseases." (PMID 36230124, 2022). "Genetic polymorphisms in ALDH2 and ADH1B significantly influence alcohol metabolism and the accumulation of toxic metabolites, thereby determining the risk of various alcohol-related diseases, including liver disease." (PMID 40943250, 2025). "It would be better to sequence the whole genome of ADH1B and ALDH2 to discover new loci that might play significant roles in the pathogenesis of CHB or other HBV-related liver diseases." (PMID 35237626, 2022). "Future research directions related to ALDH2 and liver diseases are also discussed." (PMID 32140062, 2020). "Further studies are required to determine whether ALDH2 can serve as a therapeutic target for the prevention and treatment of liver disease and cancer." (PMID 32140062, 2020). "Our study provided a novel explanation for the sensitization of HBV-infected patients to alcohol-induced liver disease and it should be worth determining whether targeting the HBx–ALDH2 interaction can be a promising pharmacological therapeutic strategy for ALD with HBV infection." (PMID 36875742, 2023). "Notably, ALDH2 deficiency partly reversed the up‐regulation of HO‐1 after CCl4 challenge, whereas administration of Alda‐1 could up‐regulate Nrf2/HO‐1 pathway as well as significantly decreased α‐SMA protein expression, which shed light on the application of Alda‐1 in clinical liver diseases." (PMID 29799157, 2018).
metabolic syndrome (14 papers, 2013 to 2026). A cluster of metabolic risk factors for CARDIOVASCULAR DISEASES and TYPE 2 DIABETES MELLITUS. "With regard to another missense variant of ALDH2, rs671, many studies have demonstrated the association of this variant with metabolic diseases/traits such as T2D, alcohol consumption, metabolic syndrome, and coronary heart disease." (PMID 30718733, 2019). "Three missense variants of metabolic syndrome-related genes, namely, rs671 in ALDH2, rs1169288 in HNF1A and rs1260326 in GCKR, significantly associate with AAT levels (P≤1.5 × 10−12)." (PMID 26174136, 2015). "For example, a deficiency of ALDH2 caused severe dyslipidemia in mice." (PMID 40137171, 2025). "The study evaluated the roles of ALDH2 in a high-fat-diet-induced metabolic syndrome in mice." (PMID 34439969, 2021). "This study evaluates the roles of ALDH2 in a high-fat-diet-induced metabolic syndrome in mice." (PMID 34439969, 2021). "Increased 4HNE adducts on ALDH2 protein in the hearts of mice with symptoms of metabolic syndrome/type-2 DM which may be the reason for the reduced ALDH2 activity." (PMID 27148058, 2016). "In addition, ALDH2 has also been shown to ameliorate HF diet-induced cardiomyopathy as well, and ALDH2-mutant mice with lower ALDH2 activity fed a HF diet exhibit greater metabolic syndrome and cardiac dysfunction." (PMID 35267991, 2022). "However, the effects of ALDH2 in modulation of metabolic syndromes remain unclear." (PMID 34439969, 2021). "However, the effects of ALDH2 in the modulation of metabolic syndromes remain unclear." (PMID 34439969, 2021).
osteoporosis (14 papers, 2010 to 2025). A condition of reduced bone mass, with decreased cortical thickness and a decrease in the number and size of the trabeculae of cancellous bone (but normal chemical composition), resulting in increased fracture incidence. "The role of ALDH2 in bone homeostasis and ethanol metabolism make it an attractive target for modulation to lower the risk of osteoporosis and fracture." (PMID 37065630, 2023). "A previous study has revealed a significant association between the ALDH2 Glu504Lys (or ALDH2*2) polymorphism and osteoporosis." (PMID 33925003, 2021). "The presence of the mutant ALDH2 Lys (or ALDH2*2) allele, particularly in women, has been found to be adversely associated with the risk of osteoporosis." (PMID 33925003, 2021). "Aldehyde-stress resulting from ALDH2 mutation accelerates osteoporosis due to impaired osteoblastogenesis." (PMID 34362382, 2021). "Among a cohort of Japanese participants, a genetic screen identified ALDH2*2 as being associated with an increased osteoporosis risk." (PMID 28474171, 2017). "Chi-square tests showed osteoporosis was significantly more frequent in the ALDH2 mutation (+) than in the (−) group." (PMID 28348376, 2017). "AAVrh.10hALDH2 is a promising therapeutic for osteoporosis in ALDH2‐deficient individuals." (PMID 37065630, 2023). "Studies in ALDH2‐deficient mice support a link between ALDH2, bone formation, and osteoporosis." (PMID 37065630, 2023). "The ALDH2E487K polymorphism (rs671; ALDH2*2 allele) is significantly associated with osteoporosis." (PMID 37065630, 2023). "Inactive ALDH2 is associated with osteoporosis, but its influence on bone metastases is unclear." (PMID 35657923, 2022). "This common ALDH2 polymorphism has a significant association with osteoporosis." (PMID 33925003, 2021). "No serious phenotype has been reported in people with dysfunctional, dominant-negative ALDH2*2 alleles, but it has been reported that they may be highly susceptible to osteoporosis and neurodegenerative diseases." (PMID 32514323, 2020). "The enzyme defect of ALDH2 has been found to adversely influence the risk of osteoporosis." (PMID 28474171, 2017). "Deficiency in ALDH2 function caused the accumulation of lipid oxidants and osteoporosis." (PMID 25006332, 2014). "In addition, previous studies have identified that polymorphisms of the ALDH2 gene, another member of the acetaldehyde dehydrogenase family, are significantly associated with osteoporosis." (PMID 20072603, 2010). "Next, we analyzed rs671 frequency in osteoporosis and normal subjects and observed ALDH2 mutation (+) frequencies of 52.8 and 35.4%, in osteoporosis and normal groups, respectively, with an odds ratio of 2.04 and a 95% confidence interval of 1.07–3.88 between osteoporosis and normal groups." (PMID 28348376, 2017). "Therefore, the loss of estrogen might increase acetaldehyde levels, resulting in an increased risk of oxidative stress and osteoporosis partly through the loss of ALDH2 protein levels." (PMID 25006332, 2014). "These transgenic mice exhibited severe osteoporosis, indicating that ALDH2 regulates physiological bone homeostasis." (PMID 30061536, 2018). "Additional confirmation of the role of ALDH activity in osteoporosis comes from the results obtained with transgenic mice expressing the Aldh2*2 (Aldh2*2 Tg) dominant-negative form of ALDH2." (PMID 30061536, 2018). "Because of the role of ALDH2 in normal bone homeostasis, ALDH2 gene therapy with AAVrh.10hALDH2 may also benefit ALDH2‐deficient individuals with osteoporosis who are not chronic alcohol users." (PMID 37065630, 2023).
Parkinson disease (14 papers, 2012 to 2024). A progressive degenerative disorder of the central nervous system characterized by loss of dopamine producing neurons in the substantia nigra and the presence of Lewy bodies in the substantia nigra and locus coeruleus. "More recently, an association between ALDH2 gene variants between language and attention dysfunction was noticed in patients with Parkinson’s disease (PD)." (PMID 29425204, 2018). "A cross-sectional case-control study has shown that ALDH2 genotype is associated with cognitive function among 139 Chinese patients with Parkinson’s disease (mean age: 63.0 years), and another study has demonstrated its association among 411 Chinese with an average age of 77.4 years." (PMID 35368830, 2021). "Thus, with respect to responsiveness to L-DOPA, the Aldh1a1/Aldh2-deficient mice model this aspect of Parkinson's disease." (PMID 22384032, 2012). "Treatment with ALDH2-specific-activator, Alda-1, significantly protects mitochondria function and reduces neuronal cell death in animal models of parkinsonism." (PMID 32832006, 2020). "In rotenone-induced mouse model of parkinsonism, ALDH2 activation using Alda-1 also attenuates rotenone-induced loss of SN TH+ dopaminergic neurons in mice." (PMID 25263579, 2015). "In this study, we investigated the neuroprotective mechanism and therapeutic effect of ALDH2 in rotenone models for parkinsonism." (PMID 25263579, 2015). "In the present study, we investigated the protective effect of ALDH2 activation in rotenone-induced cellular and animal models for parkinsonism." (PMID 25263579, 2015). "Moreover, ALDH2 has a certain protective effect in age-related disease, such as Alzheimer's Disease (AD), Parkinson's Disease (PD) and aged cardiopathy by decreasing free radicals damage." (PMID 33411685, 2020).
bone marrow failure (13 papers, 2014 to 2025). "Two enzymes, ADH5 and ALDH2, are critical in clearance of formaldehyde, whose loss results in a bone marrow failure and leukemia syndrome of purely metabolic origin." (PMID 33147438, 2020). "This study clearly shows that ALDH2 deficiency leads to a much more rapid progression of bone marrow failure." (PMID 25155611, 2014). "Recent works indicated that interruption of ALDH2 or ADH5, the major enzymes for FA degradation, may cause the accumulation of DNA damage and related diseases such as bone marrow failure, as well as dysfunction of liver and kidney." (PMID 33495458, 2021). "Mice with double knockout in ALDH2 and FANCD2 have also been found to spontaneously develop severe HSC attrition and bone marrow failure." (PMID 33573309, 2021). "The more rapid onset of bone marrow failure in Adh5−/−Fancd2−/− compared to Aldh2−/−Fancd2−/− mice, in addition to the involvement of additional tissues, suggests that the compound(s) detoxified by ADH5 are much more potent or abundant genotoxins than those cleared by ALDH2." (PMID 26412304, 2015).
Hyperglycemia (13 papers, 2014 to 2024). An increased concentration of glucose in the blood. "Finally, we want to conclude that chronic hyperglycemia-induced impaired ALDH2 activity is associated at least partially for the decreased mitochondrial respiration and ultimately enhanced hypertrophy, fibrosis, and cardiac systolic and diastolic dysfunction in the diabetic myocardium." (PMID 27736868, 2016). "Alda-1, a specific activator of ALDH2, can significantly reduce ALDH2-O-GlcNAcylation to improve I/R combined with hyperglycemia-induced infarct size, the cell apoptosis index and cardiac dysfunction." (PMID 38790676, 2024). "Research has shown that the excessive O-GlcNAcylation of the cardioprotective enzyme acetaldehyde dehydrogenase 2 (ALDH2) is the mechanism by which hyperglycemia exacerbates myocardial I/R injury of rats." (PMID 38790676, 2024). "Overexpression of ALDH2 reduces FA and reduces hyperglycemia and cognitive deficits in a diabetic mouse model." (PMID 37189611, 2023). "Therefore, in this study, we will test the hypothesis that combining both lowering cardiac 4HNE adducts by reducing hyperglycemia-mediated oxidative stress and increasing 4HNE detoxification by ALDH2 activation should ameliorate DM-associated HFpEF in ALDH2*2 mice." (PMID 36142350, 2022). "The present results were consistent with previous findings showing that ALDH2 prevented hyperglycemia-induced cellular dysfunctions in diabetic mice." (PMID 33805825, 2021). "In conclusion, in our study, ALDH2 can protect the H9C2 cardiac cells against hyperglycemia-induced inflammation by suppressing the production of mitochondrial oxygen free radicals and stimulating NLRP3 inflammasome activation." (PMID 31871948, 2019). "Alda-1, a specific activator of ALDH2, significantly decreased ALDH2 O-GlcNAc modification and improved infarct size, apoptosis index and cardiac dysfunction induced by I/R combined with hyperglycemia." (PMID 28038474, 2017). "In this study, we found a novel mechanism why hyperglycemia aggravated myocardial I/R injury, that is the fact that ALDH2, an important cardioprotective enzyme located in the mitochondrial matrix, was determined as a target for O-GlcNAc modification." (PMID 28038474, 2017). "In summary, we demonstrated that hyperglycemia increased ALDH2 O-GlcNAc modification, which contributed to the decrease of its activity, toxical aldehydes accumulation and cell apoptosis, thus resulting in the exacerbation of myocardial I/R injury." (PMID 28038474, 2017). "Based on these data, we proposed a working model predicting that ALDH2 O-GlcNAc modification was a key mechanism in hyperglycemia-exacerbated myocardial I/R injury and Alda-1 exhibited a potential therapeutic target for the treatment." (PMID 28038474, 2017). "Our results suggest that chronic hyperglycemia reduces ALDH2 activity, leading to mitochondrial respiratory dysfunction and consequently cardiac damage and dysfunction." (PMID 27736868, 2016). "The possible mechanism that we propose for this reduction is that hyperglycemia increases ROS generation which attenuates ALDH2 activity and thereby increases 4HNE adduct formation, which ultimately leads to cellular dysfunction and then death." (PMID 27882330, 2016). "Taken altogether, we suggest ALDH2 activity plays an important role in the process of hyperglycemia-induced cardiac damage." (PMID 27882330, 2016). "In the diabetic heart, hyperglycemia-induced 4HNE adduct formation on ALDH2 can reduce its activity." (PMID 27736868, 2016). "In our earlier study, we decreased cardiac 4HNE adduct levels in ALDH2*2 diabetic mice by decreasing hyperglycemia via empagliflozin (EMP), a sodium-glucose cotransporter (SGLT) 2 inhibitor, and thereby improved cardiac function via altering metabolic signaling." (PMID 36142350, 2022).
Hyperglycemia (continued). "Since myocardial I/R per se could not increase ALDH2 O-GlcNAc modification significantly, we further examined whether hyperglycemia could increase myocardial ALDH2 O-GlcNAc modification independently." (PMID 28038474, 2017). "Furthermore, we demonstrated that both acute and chronic hyperglycemia had the same effect on ALDH2 O-GlcNAc modification and I/R injury in myocardium." (PMID 28038474, 2017). "Earlier reports have shown that hyperglycemia reduced the activity and levels of myocardial ALDH2." (PMID 27882330, 2016). "We and others reported that hyperglycemia decreases myocardial ALDH2 activity in rodents." (PMID 27882330, 2016). "We hypothesized that hyperglycemia-mediated decrease in ALDH2 activity may impair mitochondrial respiration and ultimately result in cardiac damage." (PMID 27736868, 2016). "Our and other studies have demonstrated that ALDH2 could be inactivated by hyperglycemia." (PMID 28038474, 2017). "ALDH2 O-GlcNAc modification was increased by 1.16 fold in the HG+PUGNAc group compared with basal conditions, whereas hyperglycemia per se increased ALDH2 O-GlcNAc modification by 66.2%, indicating that PUGNAc could further increase ALDH2 O-GlcNAc modification under high glucose conditions." (PMID 28038474, 2017). "Therefore, the inactivation of ALDH-2 in the STZ group substantially supports the cardio-toxic phenotype of hyperglycemia and improved activity of this redox-sensitive enzyme by a high dose SGLT2i therapy clearly points to cardio-protective and anti-oxidant properties of this drug." (PMID 25402275, 2014). "Similarly, overexpression of the ALDH2 gene significantly improved cognitive function in APP/PS1 AD mice and reduced hyperglycemia and improved cognitive function by reducing FA in a mouse model of diabetes." (PMID 37693648, 2023). "In the present study, Alda-1 treatment alone improved the cardiac function and exercise tolerance without decreasing hyperglycemia but increasing 4HNE detoxification in ALDH2*2 mutant diabetic mice with HFpEF." (PMID 36142350, 2022). "In the current study, we first demonstrated that ALDH2 O-GlcNAc modification was increased under hyperglycemia with or without myocardial I/R settings." (PMID 28038474, 2017). "However, whether O-GlcNAcylation of ALDH2 could be a mechanism for its activity down-regulation and resultant aggravation of myocardial I/R injury under hyperglycemia conditions has not been elucidated, despite candidates serine/threonine residues of ALDH2 protein exist." (PMID 28038474, 2017).